PCSK9 (proprotein convertase subtilisin/kexin type 9)
Diseases named in the same sentence as PCSK9 in open-access papers (continued):
Sharing a sentence is not in itself a finding about the gene and the disease.
tumor (continued). "Additionally, the PCSK9 inhibitor combined with CD137 costimulation could slow tumor growth with enhanced recruitment of CD8+ and GzmB+ CD8+ T cells and reduction of Tregs in a syngeneic mouse model, providing a novel perspective of therapeutic strategies for future research and clinical practice." (PMID 37025995, 2023). "Only PCSK9 and RRAS were overexpressed in normal tissues, and the rest of ten genes were higher in tumor tissues." (PMID 36971680, 2023). "PCSK9 in colon cancer cells regulates EMT and PI3K signaling, enhancing tumor progression and lung metastasis." (PMID 37958351, 2023). "Targeting PCSK9 increased tumor cell MHC I expression, promoted CD8+ T cell tumor infiltration and cytotoxicity and potentiated the effects of PD-1/PD-L1 checkpoint blockade." (PMID 37568764, 2023). "PCSK9 inhibition potentiates MHC-I expression, which promotes T cells to infiltrate the tissue, making the tumor more sensitive to the immune checkpoints." (PMID 38041084, 2023). "Within this nanomedicine, the tumor matrix-targeting peptide palmitic-K(palmitic)CREKA can self-assemble into a nano-micelle to encapsulate Rapamycin (mTOR inhibitor) and SBC-115076 (PCSK9 inhibitor)." (PMID 37896137, 2023). "Overall, the discovery of PCSK9’s regulation of MHC I levels on cell surfaces represents a crucial breakthrough, providing valuable insights into immune infiltration within tumor microenvironments." (PMID 37860186, 2023). "Proprotein convertase subtilisin/kexin type 9 (PCSK9) and HMG-CoA reductase (HMGCR), both significantly high expressed in CRC tumor as ezetimibe potential targets, also confirmed of tight correlation to mTOR." (PMID 36843944, 2023). "We found that expression levels of PCSK9 and RRAS were significantly higher in normal tissue, and the rest 10 genes were overexpressed in tumor tissues." (PMID 36971680, 2023). "On the other hand, the results of other studies showed a correlation between high PCSK9 expression and HCC progression with vascular infiltration and large tumor size." (PMID 35323699, 2022). "In line with PCSK9 expression levels determining tumor size in xenograft models, datasets from human HCC tissues revealed high PCSK9 expression to correlate with microvascular invasion and large tumor size." (PMID 35162992, 2022). "PCSK9 knockout suppressed the growth of SW1116 (P < 0.01) and LOVO cells (P < 0.05) subcutaneous xenografts by over 50%, both in terms of tumor volume and tumor weight." (PMID 35803966, 2022). "Altogether, seven factors were detected both in MC38-conditioned media and MC38 tumor-bearing serum: CCL2, GDF-15, Proliferin, CXCL10, Osteopontin, PCSK9 and Serpin E1." (PMID 35962398, 2022). "PCSK9 protein and GGPP were down-regulated by R-IMPP plus simvastatin, supporting a role of GGPP inhibition in suppressing tumor growth." (PMID 35803966, 2022). "A recent study reported that PCSK9 inhibits the expression of MHC-I on tumor cells and consequently decreases tumor infiltration of cytotoxic T cells." (PMID 36110953, 2022). "Here, we showed that inhibiting either enzymes, PCSK9 or HMGCR, was effective in reducing tumoral cell growth." (PMID 36612001, 2022).
tumor (continued). "In this study, we investigated the expressions of PCSK9 in HCC cell lines and tumor samples and identified the mechanism by which HCC growth was related to changes in PCSK9 expression in vitro and in vivo." (PMID 33893729, 2021). "Monoclonal anti-PCSK9 antibody-based therapy is currently the only available treatment that can effectively reduce plasma LDL-C levels and suppress tumor growth." (PMID 34782856, 2021). "We first determined the levels of PCSK9 mRNA and protein in 48 human HCC tissues and adjacent non-tumor samples using qRT-PCR, Western blot analysis, and immunohistochemistry." (PMID 33893729, 2021). "To study the effects of PCSK9 on tumor growth in vivo, we constructed orthotopic human HCC xenograft mouse models using HCC cell lines with PCSK9 overexpression or downregulation." (PMID 33789749, 2021). "We then performed Cox proportional hazards regression analysis, with tumor depth, SCC-Ag, and PCSK9-Ab set as explanatory variables." (PMID 34504788, 2021). "RNA sequencing revealed that PCSK9 inhibition leads to the downregulation of three microRNAs, among which MIR93 and MIR194-2HG appear to play key roles in regulating proliferation and migration during tumor progression." (PMID 40563628, 2025). "PCSK9 inhibition was found to upregulate DC infiltration and MHC‐II expression, improving the activation of CD8+ T cells in the tumor immune microenvironment and effectively controlling tumor progression." (PMID 40145543, 2025). "We found significantly increasedexpressions of the PCSK6, PCSK9,MBTPS1, and FURIN genes in tumor tissue,which may indicate the involvement of these PCs in the formation andprogression of esophageal malignancies." (PMID 40264581, 2025). "Inhibition of PCSK9, either genetically or through antibodies, enhances MHC-I expression on tumor cells, suggesting that PCSK9 may influence tumor progression and therapeutic response via immune regulation." (PMID 40328788, 2025). "Although the expression of AHCY was also higher in tumor tissues than in adjacent normal tissues, it was not correlated with PCSK9 expression." (PMID 40125618, 2025). "We found that activation with metastatic colorectal carcinoma stem cell (CSC)-conditioned media significantly upregulates PCSK9 in LSECs, while media from parental tumor cells does not." (PMID 40563628, 2025). "Similarly, targeting Proprotein Convertase Subtilisin/Kexin Type 9 (PCSK9), a cholesterol metabolism regulator, through gene editing or neutralising antibodies, can increase MHC I expression on tumour cells, enhancing T cell‐mediated tumour killing." (PMID 40785042, 2025). "Inhibition of PCSK9 leads to increased expression and decreased degradation of major histocompatibility complex class I (MHC I) proteins on tumor cells, leading to increased T cell infiltration of the tumor and improved anti-tumor activity." (PMID 40507315, 2025). "Additionally, PF846, a promising intracellular PCSK9 inhibitor, demonstrated considerable therapeutic effects on ATC in vivo, inhibiting both tumor growth and metastasis." (PMID 40328788, 2025). "In addition, the inhibition of PCSK9 in tumor cells can enhance the antitumor activity of CD8 + T cells by attenuating the inhibitory effect on CD8 + T cells, thus inhibiting tumor progression." (PMID 39736777, 2024). "They indicated the potential mechanisms might be that PCSK9 promoted lysosomal degradation by physically binding to MHC-I, disrupting the recirculation of MHC-I to the tumor cell surface and thus reducing cell surface MHC-I signaling." (PMID 39736777, 2024).
tumor (continued). "PCSK9 also suppresses CD8+ T effector function by downregulating MHC I expression on tumor cells, independent of its role in cholesterol regulation." (PMID 39402302, 2024). "Their findings derived from the reduction in cholesterol levels and the enhancement of tumor necrosis factor α (TNF-α)-mediated apoptosis in the absence of PCSK9, which is detrimental to tumor development." (PMID 39736777, 2024). "Therefore, we constructed a cell line with stable knockdown of FH and PCSK9 using HCT116 cells and established subcutaneous xenograft nude mice to observe their effects on tumor growth." (PMID 38398104, 2024). "For the first time, we demonstrated that PCSK9 inhibition could promote MHC-II expression on both DCs and tumor cells in the TME, corroborating the regulatory functions of PCSK9 on MHC-II expression." (PMID 38600469, 2024). "Furthermore, the knockdown of PCSK9 decreases the expression of SMO, and its colocalization with cholesterol at the cell membrane leads to the inhibition of tumor progression." (PMID 37151886, 2023). "Results were consistent with the literature, indicating that PCSK9 gene knockout did not affect tumor growth in NCG mice." (PMID 37103355, 2023). "Meanwhile, CWR-R1ca-KD cell proliferation was not statistically different from the wild-type cells, suggesting a clear notable PCSK9 contribution to the motility but not to the tumor progression and survival." (PMID 37103355, 2023). "PRS was composed of a tumor matrix targeting peptide of palmitic-K(palmitic)CREKA, Rapamycin (mTOR inhibitor), and SBC-115076 (PCSK9 inhibitor), which could self-assemble into a uniform nanomedicine with good stability." (PMID 37896137, 2023). "Moreover, our preclinical data suggested that using hypocholesterolemic drugs, including anti-PCSK9 (Evolocumab), significantly attenuates the development of vessel co-opting CRCLM tumours." (PMID 36979711, 2023). "In addition, inhibition of PCSK9 by gene deletion or other methods promotes the action of major histocompatibility protein class I (MHC I) proteins on cancer cells and enhances tumor infiltration of T cells." (PMID 36080373, 2022). "In accordance with some findings, it has been clarified that inhibiting PCSK9 may induce the infiltration of T lymphocytes in to the TME, subsequently provoking tumor cells to respond to immune checkpoint therapy." (PMID 36552048, 2022). "Furthermore, we produced an in vivo tail vein-lung metastasis model by injecting PCSK9-silencing HT-29 cells into BALB/C nude mice, and 5 weeks later, the mice showed obvious emaciation and were sacrificed for analysis of tumor cell lung metastasis." (PMID 36242053, 2022). "During the experiment, one mouse with injection of PCSK9-silencing tumor cells died and the necropsy showed no tumor liver and lung metastasis." (PMID 36242053, 2022). "The depletion of PCSK9 in tumors increased the intratumoral infiltration of lymphocytes, such as CD8+ cytotoxic T-cells (CTLs), CD4+ T helper (Th) cells, γδT cells and natural killer (NK) cells, thus rendering the tumor responsive to immune checkpoint therapy." (PMID 36552895, 2022). "Moreover, evolocumab (an inhibitory monoclonal antibody to PCSK9) treatment, alone or in combination with anti-PD1 treatment, also inhibited the tumor growth of cells resistant to immune checkpoint therapy." (PMID 36552895, 2022). "PCSK9 expression was decreased in most HCC samples relative to non-tumor samples (n = 34 vs. n = 14)." (PMID 33893729, 2021).
tumor (continued). "PCSK9 inhibition, either through genetic deletion or administration of monoclonal antibodies, increased MHC-I expression on the tumor cell surface and thus enhanced tumor infiltration by cytotoxic T cells." (PMID 35097027, 2021). "Inoculation of PCSK9 knock out cells into immunodeficient mice did not result in tumor growth attenuation, which hinted to the possible involvement of immune cells in the response to PCSK9 deletion." (PMID 33677469, 2021). "Scavenger receptor BI, proprotein convertase subtilisin/kexin type 9 (PCSK9), apoE and apoAII were similar in tumor and non-tumor tissues." (PMID 34629057, 2021). "Further, consistent with earlier study, in this work, we report increase in serum levels of murine PCSK9 in presence of tumor as compared to mice without tumor." (PMID 30386595, 2018). "As shown in the schematic table, upon glucose feeding, PCSK9 level in serum as well as in tumor tissue was elevated in mice with tumor-graft (group IV) as compared to tumor-bearing mice without glucose feeding (group III)." (PMID 30386595, 2018). "In our study, the systemic levels of PCSK9 did not correlate well with the presence or absence of tumor." (PMID 26674961, 2015). "Furthermore, methionine supplementation increased the mRNA transcription of PCSK9 in CRC tumor cell line but not in liver cell line." (PMID 40125618, 2025). "Furthermore, flow cytometry detection demonstrated that PCSK9 inhibition increased the infiltration ratio of CD8+ T cells (P = 0.0015) and DCs (P = 0.0024) and promoted the expression of MHC-II (P = 0.0097) on the surface of tumor cells." (PMID 38600469, 2024). "On one hand, PCSK9 could downregulate the expression of major histocompatibility complex-I (MHC-I) molecules on the surface of tumor cells through lysosomal degradation and downregulate tumor-infiltrating cytotoxic T lymphocytes (CTLs)." (PMID 38600469, 2024). "To further confirm whether this relationship existed in NSCLC tissue between PCSK9 expression with density and distribution of intratumoral CD8+ T cells, we examined tumor cells and CD8+ T cells in PCSK9hi and PCSK9lo NSCLC tissues by multiplexed immunofluorescent staining." (PMID 37025995, 2023). "To confirm whether this phenomenon existed in NSCLC tumor tissue between different PCSK9 expression levels and CD8+ T cells, we next performed multiplexed immunofluorescent staining to show tumor cells and CD8+ T cells in NSCLC tissue with different PCSK9 expression levels." (PMID 37025995, 2023). "Nevertheless, tumor and nontumor tissues seem to differentially regulate PCSK9 expression." (PMID 35162992, 2022). "Whether or not circulating levels of PCSK9 can partly originate from the tumor itself is an open question that needs to be addressed." (PMID 36203122, 2022). "Although, tumor size was not affected for the short duration of the experiment, tumors were noticeably impeded in the absence of PCSK9 compared to control tumors as assessed by the disappearance of bleeding and coagulation areas and of large vessels in tumoral tissue." (PMID 36612001, 2022). "PCSK9 inhibited HCC cell proliferation, cell cycle progression, and apoptosis by interacting with GSTP1 and suppressing JNK signaling, suggesting that PCSK9 might act as a tumor suppressor and be a therapeutic target in HCC patients." (PMID 33893729, 2021). "Since the mRNA and protein levels of PCSK9 were elevated in tumor tissues of glucose provided, tumor-bearing mice than the tumor-bearing mice without glucose feeding, the transcriptional regulation of PCSK9 by glucose is likely to be responsible for the enhanced serum level of PCSK9." (PMID 30386595, 2018).
tumor (continued). "We found that grade of tumor did not correlate with PCSK9 staining (p-values > 0.30)." (PMID 26674961, 2015). "We treated grade of tumor and stage of fibrosis as ordered values and employed spearman correlation test to examine whether there were non-zero correlations between grade of tumor (or stage of fibrosis) and PCSK9 staining." (PMID 26674961, 2015). "Importantly, PCSK9 can reduce the expression of major histocompatibility complex (MHC) I protein on the surface of tumor cells, weaken T-cell receptor circulation and signal transmission, and inhibit the tumor infiltration and anti-tumor activity of CD8+ T cells." (PMID 38398104, 2024). "Notably, we first found that dendritic cell (DC) infiltration and major histocompatibility complex-II (MHC-II) expression could be upregulated by PCSK9 inhibition and improve CD8+ T cell activation in the tumor immune microenvironment, thereby achieving potent tumor control." (PMID 38600469, 2024). "Therefore, in the work outlined here, it is essential to analyze whether glucose feeding modulates endogenous (murine) PCSK9 in both presence and absence of tumor." (PMID 30386595, 2018). "The result showed that blocking PCSK9 with alirocumab, a clinically approved PCSK9 neutralizing antibody, did not halt MSS CRC tumor progression, akin to anti‐PD‐1 therapy." (PMID 40125618, 2025). "Moreover, PCSK9 deficiency failed to retard tumor growth in mice depleted of CD8+ T cells, while depletion of CD4+ T cells had hardly any impact, which led CD8+ cytotoxic T cells (CTLs) to be identified as the most critical for the anti-tumor effect of PCSK9 deficiency." (PMID 33677469, 2021). "In our study, we objectively found that by immunohistochemistry, PCSK9 was much less present in HCC than adjacent cirrhotic liver tissue, independent of tumor grade." (PMID 26674961, 2015). "By decreasing cholesterol and lipid raft levels in the plasma membrane, proprotein convertase subtilisin/kexin type 9 (PCSK9) boosts human epidermal growth factor receptor 1 and 3 (EGFR and HER3) activation, driving tumor growth and metastasis in triple‐negative breast cancer (TNBC)." (PMID 40192514, 2025).